ENSG00000261793 (novel transcript, TMEM210 and LRRC26 readthrough)
Gene: Protein-coding gene on chromosome 9 (137,168,854 to 137,171,984, reverse strand). Ensembl gene ENSG00000261793.
Genetic constraint (gnomAD): Loss-of-function variants: 2 observed, 2.47 expected, observed/expected ratio (o/e) 0.81, 90% interval 0.31 to 1.82. That is too few expected variants to judge how well the gene tolerates losing a copy. Missense variants: 36 observed, 24.04 expected, observed/expected ratio (o/e) 1.5, 90% interval 1.14 to 1.89. Synonymous variants: 19 observed, 9.98 expected, observed/expected ratio (o/e) 1.9, 90% interval 1.23 to 1.97.